TERT (telomerase reverse transcriptase)
Diseases named in the same sentence as TERT in open-access papers (continued):
Sharing a sentence is not in itself a finding about the gene and the disease.
cancer (continued). "Multiple transcription factors including Myc, NF-kB, β-catenin have been identified to regulate TERT transcription however how constitutive activation of TERT transcription in multiple cancer cell types is achieved remains an intriguing area of investigation." (PMID 32674474, 2020). "However, at the allele-level, we generally found that hypermethylation of promoter sequences in cancer cells is associated with repressed expression, and the remaining unmethylated alleles marked with open chromatin are largely responsible for the observed TERT expression in cancer cells." (PMID 32468444, 2020). "In summary, our study provided a new insight into the mechanisms of TERT upregulation in cancers with low frequency of TPMs." (PMID 33061812, 2020). "The prevalence of TERT upregulation in cancer implicates that it has pro-malignant activities in addition to telomere maintenance." (PMID 32599885, 2020). "TERT is highly transcribed in germ cells, stem cells, and cancer cells, but is barely detectable in most somatic cells." (PMID 33239622, 2020). "The transcription of TERT is regulated by many positive and negative factors, and SP1 and Myc are two common transcription factors that activate TERT expression in cancer cells." (PMID 33239622, 2020). "In this patient, KRAS was the only additional cancer gene besides FOXL2 and TERT that was mutated in all samples." (PMID 32455687, 2020). "TERT mutation was significantly associated with high TMB score and neoantigen load in all cancer types." (PMID 32810393, 2020). "The overall pattern of TERT promoter methylation is relatively conserved across a range of cancer tissue types, particularly in a proximal hypomethylated region, in alignment with previous studies." (PMID 33245585, 2020). "Here we identified the TERT gene as the first choice to develop efficient gene editing strategies towards the goal of gene editing therapy for cancer." (PMID 31963842, 2020). "An exploratory study involving heterogeneous cohorts of cancer patients indicated that ∼60% of cases expressed detectable levels of TERT." (PMID 33391635, 2020). "Our work demonstrates that gene editing-mediated TERT knockout is a potential therapeutic option for treating cancer." (PMID 31963842, 2020). "The PIK3CA/Akt signaling pathway is involved in cellular self-renewal in embryonic stem cells and cancer stem cells, as well as in TERT Ser227 and Ser824 phosphorylation, subsequent nuclear translocation, and cellular transformation." (PMID 32204305, 2020). "Highly recurrent mutations (C228T and C250T) in the promoter region of TERT can drive TERT transcriptional activation and over-expression in cancer." (PMID 32468444, 2020). "Considering the association between TERT expression and KRAS mutation, therapeutic drugs targeting this pathway can be developed for cancer prevention." (PMID 32932803, 2020). "As supported by this view, our recent TCGA analyses have demonstrated that both HMGA2 and TERT expression levels were raised in the alterations of the TGF-β pathway genes in 33 cancer types." (PMID 32577156, 2020). "Cancer lines often contain more than two TERT gene copies, with considerable line‐to‐line and cell‐to‐cell heterogeneity." (PMID 33245585, 2020). "They will be presented in the last two chapters of this review, together with potential consequences of TERT telomere-unrelated functions for the development of anti-cancer strategies and applications of TERT as a potential therapeutic target." (PMID 33329574, 2020). "The genomic region on chromosome 5 at 5p15.33, harboring TERT and cleft lip and palate associated transmembrane 1-like protein (CLPTM1L) genes, has been reported to contain several independent cancer susceptibility loci." (PMID 32121056, 2020). "We next identified CpGs that were differentially methylated between WT and TERT promoter mutant cancers." (PMID 32468444, 2020).
cancer (continued). "Several cancers harbor various genomic alterations in TERT with most of them correlating with TERT expression level, telomerase activity, and telomere length." (PMID 32674474, 2020). "TERT reactivation is important for cancer cells, as cancer cells have significantly shorter telomeres." (PMID 32849278, 2020). "Briefly, TERT is expressed in cancer stem cells and progenitor cells, where it is indispensable for self-renewal." (PMID 32630460, 2020). "Telomerase inhibitors such as small molecule inhibitors, antisense nucleotides, G-quadruplex stabilizers, TERT-dependent anticancer immunotherapy, and chemical inhibition of telomerase are the most commonly studied anti-cancer treatment strategies." (PMID 32121056, 2020). "This valuable dataset represents the most extensive characterization of TERT promoter methylation in cancer cells to date and will help guide the future study of transcriptional regulation of telomerase." (PMID 32920953, 2020). "The RB/E2F gene regulatory circuit regulates TERT promoter activity during liver regeneration and cancer." (PMID 32722302, 2020). "First clinical trials of DNA vaccine based on TERT applied in cancer patients reported it to be safe, well tolerated, and immunogenic, immunization resulting in disease stabilization in 58% of patients with relapsed or refractory cancers." (PMID 32570805, 2020). "In cancer cells, TERT is transcriptionally reactivated by oncogenic transcription factors such as Myc, NF-κB, β-catenin, and SP18,11,12, and TERT expression is elevated in HCC patients and positively correlated with the incidence and development of HCC13,14." (PMID 33239622, 2020). "This interesting example of a cancer with mono-allelic TERT expression provides further evidence that TERT promoter DNA methylation is associated with inactive alleles." (PMID 32468444, 2020). "In ≈ 22% of cancer cell lines, TERT reactivation is clearly genetic, occurring through activating promoter mutations." (PMID 33245585, 2020). "First, DYRK2 regulation of c-Jun, c-Myc, Rpt3, TERT, and katanin p60 reveals the implication of this kinase in cell-cycle-mediated cancer development." (PMID 32462403, 2020). "A subset of the cancer cell lines with WT TERT promoters employed the telomerase-independent, Alternative Lengthening of Telomeres (ALT) mechanism for telomere maintenance." (PMID 32468444, 2020). "Interestingly, the authors could show on an allele level that the hypermethylation of TERT promoter sequences in cancer cells is associated with TERT repression, while the remaining unmethylated allele marked with an open chromatin is largely responsible for the TERT expression in cancer cells." (PMID 32722302, 2020). "A growing body of evidence indicates that the expression of TERT, the catalytic subunit of telomerase, is a biological marker of progression in several cancers." (PMID 31772219, 2019). "The long-read sequencing data of TERT in mouse and human cells reveals a remarkable evolutionary trade-off between telomerase regulation and growth/cancer." (PMID 30568224, 2019). "Numerous clinical studies have evaluated telomerase/TERT-related alterations as prognostic factors for cancer patients." (PMID 31285550, 2019). "TERT participates in important physiological processes and contributes to multiple cancer hallmarks by regulating DNA methylation and chromatin remodeling activity." (PMID 31284662, 2019). "Here, we present an overview of the mechanistic insights into cancer-specific TERT expression and biological/clinical implications, paying special attentions to the contribution of genomic aberrations to the TERT trans-activation." (PMID 31285550, 2019). "Both CCNB1 and TERT consistently showed higher expression levels in cancer tissues of three types than in normal tissues." (PMID 31856825, 2019).
cancer (continued). "The partial influence (PI) of TERT on TEL pathway activity is highest in all cancer subtypes in contrast to TERT differential expression, presumably due to the stabilizing effect of the interaction partners of TERT in its local pathway topology." (PMID 31750255, 2019). "The immortality of cancer is maintained by constitutive TERT expression, which means that the intracellular environment is rich in various factors that activate TERT promoters, while the promoter remains largely inactive in most normal cells." (PMID 31035374, 2019). "Similar to the application discussed in Section 3.1, the human TERT promoter can enable cancer-specific replication of adenoviruses by controlling the key replicative genes (such as viral E1A gene), ultimately generating oncolytic adenoviruses." (PMID 31035374, 2019). "Together, these findings showed that modification of the TERT promoter was necessary to improve both the cancer specificity and cytolytic effect of the oncolytic adenovirus." (PMID 31035374, 2019). "To evaluate their relationship in cancer, we examined the Cancer Genome Atlas (TCGA) dataset via cBioPortal and observed a consistent positive correlation between TERT and DNMT3B expression in the majority of cancer types." (PMID 31284662, 2019). "Cancer cells become immortalized through telomere maintenance mechanisms, such as telomerase reverse transcriptase (TERT) activation." (PMID 31179925, 2019). "This allows TERT promoter-driven gene expression to occur in a cancer-specific manner in the majority of cancers, as ~85% of all cancers exhibit overexpression of TERT." (PMID 31035374, 2019). "Second, β-Catenin directly activates the transcription of the TERT gene in both mouse embryonic stem cells and in human cancer cells." (PMID 31284662, 2019). "Genes of the DKC1 and TERT branches of the TEL-TMM were commonly up-regulated in all three cancer types, which resulted in the markedly increased PSF-score along these pathway branches." (PMID 31750255, 2019). "Consistently, TERT expression/telomerase activity is detectable in up to 90% of human primary cancers." (PMID 31285550, 2019). "The cancer genomic landscape mapping has recently identified both rearrangements and oncogenic viral genome insertions at the TERT locus as novel mechanisms to upregulate TERT expression by hijacking enhancers." (PMID 31285550, 2019). "Telomerase reverse transcriptase (TERT) is a catalytic component of human telomerase, undetectable in normal somatic cells but upregulated in cancers and stem cells, where telomere length is maintained by telomerase." (PMID 31930133, 2019). "Higher TERT expression in tumors was observed to predict poor patient outcomes in a panel of cancer types." (PMID 31285550, 2019). "This pan-cancer applicability of the human TERT promoter is important when considering that most other cancer-specific promoters are only capable of selectively targeting a small subset of cancers in a tissue-specific manner." (PMID 31035374, 2019). "Human TERT is overexpressed in >90% human cancers meaning that is it close to being a universal TAA." (PMID 31164958, 2019). "We estimated telomere length and TERT levels and their relationship in cancer tissue, SM, and peripheral blood, and we investigated their predictive and prognostic roles in patients with HNSCC." (PMID 31772219, 2019). "It has also been revealed that TERT displays a RNA-dependent RNA polymerase (RdRP) activity, thereby regulating mitotic progression and cancer stem cell traits." (PMID 31285550, 2019). "Alternative applications within the scope of gene therapy exploiting constitutive activation of TERT in cancer utilize silencing or inhibition of TERT or TERC activity." (PMID 31035374, 2019).
cancer (continued). "We performed a systematic analysis of TERT high (TERThigh) and low (TERTlow) cancers using multidimensional data from The Cancer Genome Atlas (TCGA)." (PMID 31179925, 2019). "The monitoring of anti-TERT Th1 response as potential biomarker for immunotherapy is currently evaluated in several cancers (NCT02840058)." (PMID 31358938, 2019). "TERT is also required for symmetric stem cell division and its high expression significantly increases cancer stem cell (CSC) pool and self-renewal in prostate cancer." (PMID 31285550, 2019). "The enhanced EMT, stemness, and MMP expression all contribute to invasiveness and metastasis in cancer, which indicates an important role of TERT in cancer progression." (PMID 31285550, 2019). "TERT levels in SM were significantly higher in patients with cancer of the hypopharynx/larynx (P = 0.013) and in those with advanced stage disease (P = 0.002)." (PMID 31772219, 2019). "Because very short telomeres are the most frequent genomic alteration in human tumors, TPE-OLD likely plays a part in TERT/telomerase activation in cancer cells." (PMID 31285550, 2019). "Given the widespread of TERT/telomerase activation and its critical role in malignant transformation, great efforts have been made to dissect how the TERT gene is de-repressed and telomerase is activated in cancer cells." (PMID 31284662, 2019). "Recently, telomerase reverse transcriptase (TERT) promoter methylation aberration has been found in a large number of cancers, in a region described as TERT hypermethylated oncological region (THOR)." (PMID 31921291, 2019). "The most frequently adopted strategy for telomere maintenance by cancer cells is reactivation of TERT, which is upregulated in ~85% of clinical cases." (PMID 31035374, 2019). "Activities of TERT are frequently up-regulated in human cancers, which is thought to be a critical mechanism contributing to human tumorigenesis." (PMID 30625996, 2019). "Consistently, TERT expression and telomerase activity is detectable in up to 90% of human cancer-derived cell lines and primary tumors." (PMID 31284662, 2019). "Among the significant prognostic gene pairs, the gene pair CCNB1_TERT is the only prognostic gene pair shared by the three types of cancer." (PMID 31856825, 2019). "These works illustrated that human TERT promoter-driven gene therapeutics can target a wide range of cancers and express therapeutic genes in a safe manner." (PMID 31035374, 2019). "Molecular alterations in the TERT promoter lead to enhanced expression of telomerase, which maintains telomere length thereby letting the cancer cells to continuously proliferate and inhibiting the programmed cell death and apoptosis." (PMID 31126249, 2019). "The cancer-specific TERT expression and telomerase activation has always aroused great enthusiasm in the potential clinical application of TERT/telomerase-based assays in the cancer field." (PMID 31284662, 2019). "Despite short telomeres, high telomerase activity and TERT expression were observed in PTCs as in other human cancer tissues." (PMID 31200515, 2019). "High levels of TERT transcripts in cancer cells represent a reliable prognostic marker for identifying HNSCC patients with risk of progression." (PMID 31772219, 2019). "TERT, however, is expressed in most cancer cells, some adult stem cells and some proliferating cells such as human T cells and B cells." (PMID 31781563, 2019). "Between the premalignant stage and cancer, TERT expression is thus reactivated resulting in unlimited cellular proliferation and tumorigenesis, as described during hepatocarcinogenesis (HCC) to enable malignant transformation and HCC development." (PMID 32082377, 2019). "In conclusion, high levels of TERT transcripts in cancer cells represent a reliable prognostic marker for identifying HNSCC patients with worse response to treatment and risk of progression." (PMID 31772219, 2019).
cancer (continued). "Cancer-specific TERT expression and telomerase activation has always aroused great enthusiasm for a potential clinical application of TERT/telomerase-based assays in the cancer field." (PMID 31285550, 2019). "A common single-nucleotide polymorphism (SNP) in the TERT promoter, rs2853669 (c.-245A>G), previously studied in several cell lines and cancer cohorts, has been suggested to alter promoter-mediated TERT expression by impacting E2F1 or ETS/TCF binding." (PMID 31395865, 2019). "The pyrosequencing analysis revealed that a significant demethylation in the PTEN promoter occurred in TERT-depleted cancer cells, which was coupled with the DNMT3B down-regulation in these cells." (PMID 31284662, 2019). "For example, the WNT/β-Catenin pathway directly activates TERT transcription and telomerase in both normal stem cells and cancer cells." (PMID 31284662, 2019). "These new findings not only lead to profound mechanistic understanding of the cancer-specific TERT transcription, but also provide useful tools for clinical managements of cancer patients." (PMID 31285550, 2019). "Further studies are required for the rational development of TERT-based cancer therapeutic interventions." (PMID 31285550, 2019). "Compelling evidence has also accumulated that TERT contributes to cancer development and progression via multiple activities beyond its canonical telomere-lengthening function." (PMID 31285550, 2019). "TERT activity is frequently upregulated in human cancers and it is thought to be a critical mechanism that contributes to human tumorigenesis." (PMID 31482066, 2019). "The high prevalence of TERT reactivation in cancer patients and its integral role in cancer immortality indicate TERT as an attractive therapeutic target for cancer therapy." (PMID 31035374, 2019). "The increased AKT phosphorylation and super-activation is observed in cancer cells over-expressing TERT, thereby promoting cellular proliferation, survival, and oncogenic potentials." (PMID 31284662, 2019). "The hypermethylated THOR is a key TERT-upregulating mechanism in cancer, responsible for telomerase activation in 90% of human malignancies." (PMID 31284662, 2019). "TERT has been reported to be activated in cancer cell lines and plays an important role in growth, migration and invasion of cancer cells." (PMID 31666098, 2019). "Recently, TERT overexpression has been demonstrated to promote invasion in cancer cells through the acquisition of an invasive mesenchymal phenotype (epithelial-to-mesenchymal transition) and stem cell-like traits." (PMID 30884806, 2019). "TERT promoter hypermethylation is very common in many cancers contrarily to normal cells, and a positive correlation was found between TERT methylation and TERT expression, especially in epithelial tumors." (PMID 31291979, 2019). "To address these questions above, we assembled genome-wide molecular data across 8 cancer types in The Cancer Genome Atlas (TCGA) and performed comprehensive pan-cancer analysis by comparing TERT high (TERThigh) and low (TERTlow) groups." (PMID 31179925, 2019). "Despite numerous reports showing that human TERT promoter can endow cancer specificity to gene therapeutics, the promoter induces relatively weak transgene expression." (PMID 31035374, 2019). "By means of the mutations of the telomerase reverse transcriptase (TERT) promoter and ATRX/DAXX, cancers can immortalize and escape cell senescence and apoptosis." (PMID 30625996, 2019). "In support of critically short telomeres being a determinant of aging and longevity, we previously showed that increased TERT expression in the context of cancer resistant transgenic mice was sufficient to delay aging and extend mouse longevity by 40%." (PMID 31140977, 2019).